HK2 (hexokinase 2)
Diseases named in the same sentence as HK2 in open-access papers (continued):
Sharing a sentence is not in itself a finding about the gene and the disease.
tumor (continued). "Taken together, the combination of HK2 depletion and metformin treatment could lead to more tumor cell apoptosis and reduce tumor growth." (PMID 32083006, 2020). "Similarly, HK2 silencing in combination with sorafenib produced the same effect in inhibiting HCC tumour growth." (PMID 33092283, 2020). "Therefore, HK2 is confirmed to play an important regulating rule in glucose metabolism and as a tumour promoter in multiple cancers." (PMID 32279420, 2020). "In mouse models, HK2 plays a vital role in tumor initiation and maintenance." (PMID 32042322, 2020). "Therefore, our data supported that HK2 expression is higher in GBM tumours, especially in chemoresistant GBM patients." (PMID 32279420, 2020). "HK2 (hexokinase), one of the three key rate-limiting enzymes of glycolysis, could be involved in tumor progression by miRNA adjusting." (PMID 33204264, 2020). "However, a soft agarose assay showed the synergistic effects of metformin and HK2 silencing on anchorage-independent growth of tumor cells." (PMID 32083006, 2020). "Furthermore, the authors observed that, the use of FDA-approved therapeutic drug for HCC, sorafenib coupled with HK2 depletion decreased tumor growth more extensively that each standalone treatment." (PMID 33182674, 2020). "Indeed, flow cytometry showed that the rate of tumor cell apoptosis did increase with either HK2 silencing or metformin treatment alone, or in combination, and increased more by treatment of both lonidamine and metformin." (PMID 32083006, 2020). "On the contrary, increased hexokinase 2 expression in tumor microenvironment leads to inhibition of extracellular glycolysis, decreased Ca2+ flux in T cells, decreased immune cell effector function, and promoted tumor evasion from T‐cell–mediated immune monitoring." (PMID 32875727, 2020). "HIF‐1α, GLUT1, and HK2 were stained and demonstrated in tumor cells." (PMID 32533646, 2020). "Overexpression of HK2 promotes cancer cell survival, in which tumor cells may escape apoptosis and closely related to chemo/radiotherapy resistance." (PMID 32424132, 2020). "Interestingly, Hk2, which is known to be highly expressed in many cancers, promotes tumor initiation and oncogenic transformation and was selectively inhibited by BRB during experimental oral carcinogenesis." (PMID 31336728, 2019). "Similarly, glucose uptake is also reduced by BBR, via inhibition glucose transporter 1 (GluT1), lactate dehydrogenase-A (LDH-A), and hexokinase-2 (HK-2) expression, which induces apoptosis and thus inhibits tumor growth and invasiveness." (PMID 31841506, 2019). "Significantly reduced tumor growth was detected in HK2 knockdown mice." (PMID 31212816, 2019). "Applying the concept of combinational therapy for cancer, HK2 inhibition could enhance the response rate of PD-1/PD-L1 therapy by releasing immune cells from metabolic competition and directly increasing tumor cell apoptosis." (PMID 31718692, 2019). "Moreover, the expression of HK2 alters the metabolic phenotype and supports the continuous growth of tumor cells, making it an attractive target for cancer therapy." (PMID 31137633, 2019). "We next determine whether HectH9 and its mediating HK2 ubiquitination are necessary for tumor development." (PMID 31201299, 2019). "These combined treatments may represent a pertinent approach to induce metabolic catastrophe and death of tumor cells through CMA-mediated HK2 degradation." (PMID 31623164, 2019). "HK2 abrogation impeded in vivo tumor growth and dissemination." (PMID 31212816, 2019). "In addition to HK1, there are three other enzymes of HK identified, out of which hexokinase 2 (HK2) is the major enzyme that is closely involved in tumor cell glycolysis." (PMID 31850189, 2019). "The tumor xenograft growth was inhibited after HK2 knockdown in vivo." (PMID 31426130, 2019). "HK2 downregulation inhibits the regulatory factors of tumor metabolism." (PMID 31569385, 2019).
tumor (continued). "Regarding functional aspects of the immune responses, our results suggest that PD-L1-mediated HK2/glycolysis upregulation of tumor cells might dampen T-cell function in the TME of NSCLCs." (PMID 31718692, 2019). "To ascertain whether HectH9 regulates tumor sphere formation through HK2, we silenced endogenous HectH9 expression in HK2-overexpressing cells and found that HK2-enhanced CSC self-renewal ability was abolished upon HectH9 depletion." (PMID 31201299, 2019). "Moreover, we verified a positive correlation between the expression of B7-H3 and HK2 in tumor tissues of CRC patients." (PMID 30952834, 2019). "However, systemic knockout of HK2 in mice bearing lung cancer has shown profound therapeutic effects on tumor metabolism and growth, with minimal adverse effects to normal mouse physiology." (PMID 31450721, 2019). "Previous studies have shown that the expression of HK2 could be regulated by STAT3 in tumor cells such as MCF7, HepG2, and A549 cells." (PMID 30952834, 2019). "Moreover, we found that the defect in HK2 ubiquitination suppressed tumor growth to a degree similar to HectH9 knockdown." (PMID 31201299, 2019). "ErbB2 overexpression and KRAS oncogenic mutations also contribute to the selective HK2 induction in tumor tissues, though the mediating machinery is not completely understood." (PMID 31201299, 2019). "In addition to its canonical metabolic roles in tumor or cardiac tissues, HK2 translocates to the nucleus or mitochondria and triggers an autophagic and anti-apoptotic responses through its interaction with the voltage-dependent anion channel (VDAC)." (PMID 31428089, 2019). "The result showed that HK2 expression was higher in tumor samples compared with peritumor tissues." (PMID 31426130, 2019). "Recently, studies have documented that Akt-mTOR pathway could modulate HK2, a pivotal role in the procession of cancer metabolism, leading to tumor rapid growth, even in the presenceof oxygen." (PMID 31137633, 2019). "Although oncogenic mutations affect tumor cell metabolism, the relationship of PD-L1 and HK2 expression was not affected by EGFR mutation status in NSCLCs." (PMID 31718692, 2019). "However, the combination of sorafenib and HK2 depletion decreased tumor growth much more substantially." (PMID 29386513, 2018). "In different tumor types including breast, colon, and in GBM stem-like cells, miR-143 has been linked to glucose metabolism and regulation of cancer glycolysis via targeting hexokinase-2." (PMID 30322013, 2018). "However, the combination of HK2 knockdown and etoposide prohibited tumor growth by both decreased proliferation and increased cell death." (PMID 29687779, 2018). "Furthermore, HK2 is required for tumor initiation and maintenance, and is a key mediator of aerobic glycolysis, promoting tumor metastasis and growth in many types of cancers." (PMID 29985480, 2018). "Likewise, the machinery of glycolysis, enzymes such as pyruvate kinase type M2 and hexokinase 2, is particularly active and ultimately leads to both lactate and tumor formation." (PMID 30631356, 2018). "LMP1 could upregulate hexokinase 2 (HK2) via activation of c-Myc, upregulation of HK2 could also promote aerobic glycolysis and facilitate growth of tumor cells by blocking apoptosis under hypoxic conditions." (PMID 29617291, 2018). "To determine whether HK2 T473 phosphorylation also rendered a growth advantage to tumor cells in vivo, we performed xenograft studies." (PMID 29985480, 2018). "Tumor sections were analyzed for cell death, using anti-cleaved caspase 3, in mice treated with sorafenib in combination with HK2 depletion and showed about 2-fold increases in cell death compared to mice with HK2 depletion alone or mice treated with sorafenib alone." (PMID 29386513, 2018). "Hepatic HK2 deletion inhibits tumor incidence in a mouse model of hepatocarcinogenesis." (PMID 29386513, 2018).
tumor (continued). "The phosphorylation of HK2 at Thr473 by AKT promotes its mitochondrial association to protect cardiomyocytes, and AKT inhibitor can decrease the location of HK2 to the outer mitochondrial membrane to inhibit glycolysis in tumor cells." (PMID 29985480, 2018). "Importantly, in vivo administration of cysteamine strongly reduced tumor size with partial (Glut1, Pdk1, and Hk2) modification of their hypoxic transcriptional signature but without affecting their differentiation status." (PMID 30456364, 2018). "Also, we found higher transcript levels of SLC2A1 and HK2 in C-PDAC tumours relative to EL-PDAC tumours and the highest SLC2A3 transcript levels in QM-PDAC tumours." (PMID 30018740, 2018). "In addition, HK2 knockdown has been found to successfully inhibit tumor growth in glioblastoma, medulloblastoma and renal cell carcinoma." (PMID 28915575, 2017). "Knocking down HK2 expression inhibited tumour growth by 44.9% at day 28 after transplantation." (PMID 27926482, 2017). "In tumor cells, HK2 plays a critical role at the focus point of two central pathways of glycolysis control – c-Myc and hypoxia-inducible factor 1-alpha (HIF1α) pathways to provide tumor cells with energy and metabolic compounds for the synthesis of nucleotides and proteins." (PMID 28415659, 2017). "HK2 plays a pivotal role in the process of tumor glycolysis regulation." (PMID 28427230, 2017). "Positive HK2 expression showed poor OS in all tumor types (HR = 1.75 [1.41-2.18], P < 0.001)." (PMID 28415659, 2017). "This high rate of glycolysis in tumor cells, including gioma cells, was presumably ascribed to up-regulation of key catalytic enzymes in glycolysis, especially hexokinases, more specifically hexokinase 2 (HK2)." (PMID 29220380, 2017). "The current study shows that HK2 is required for primary tumor growth and metastasis in PDAC." (PMID 28915575, 2017). "Therefore, the overproduction of HK2 in tumor cells provides both a metabolic benefit and an apoptosis evasive capacity, resulting in uncontrolled tumor proliferation within the host's tissues and drug resistance to chemotherapy." (PMID 28415659, 2017). "Furthermore, treatment with 2-DG and CQ represses HK2-mediated Warburg effect and ULK1-dependent autophagy activates apoptosis to cause tumor regression." (PMID 29285270, 2017). "In addition, miR-155 levels were shown highly indicative of the clinical response to aromatase inhibitors as one of its targets, Hexokinase 2 (HK2), is involved in the adaptation of tumor cells to aromatase inhibitors." (PMID 28994735, 2017). "Regulation of HK2 by miR-125a may explain why the down-regulation of miR-125a during HCC carcinogenesis promotes tumor growth and Warburg effect." (PMID 28596599, 2017). "In contrast, HK-2 was substantially overexpressed in tumor samples (n = 75, p < 0.001)." (PMID 28320429, 2017). "The regulation of HK-2 expression in tumor cells is complicated." (PMID 28320429, 2017). "Although HK2 is a novel anti-tumor target, there are few potent HK2 inhibitors identified." (PMID 28427443, 2017). "Interestingly, we found that HK1 and HK2 can distinctively regulate the adaption of tumour cells to different energy status." (PMID 28054552, 2017). "HK2 plays essential roles in tumour growth, survival, and metastasis." (PMID 29156804, 2017). "Next, we investigated whether the miR-125a/HK2 axis inhibits HCC xenograft growth through regulating tumor glycolysis." (PMID 28596599, 2017). "Moreover, the dual role of HK2 in tumor cells makes it an attractive target for anti-cancer therapy." (PMID 28415659, 2017). "Indeed, preventing HK2 expression with a short hairpin RNA (shRNA) impeded cancer cell survival and inhibited tumour growth in a xenograft model." (PMID 27926482, 2017). "However, the mechanisms for the HK2-mediated tumor migration and invasion are still under investigation and more functional targets of miR-143 in OSCC require further discovery." (PMID 28174335, 2017).
tumor (continued). "Previous work from our group has shown that loss of HK2 diminishes GBM growth, and that HK2 is both tumor specific and not significantly expressed in normal adult human or murine brain." (PMID 27588472, 2016). "Knockdown HK2 significantly reduced xenograft tumor growth with less Ki67 expression (P = 0.0048)." (PMID 26884725, 2016). "The link between HK2 overexpression and highly glycolytic malignant tumors was first demonstrated by mRNA analysis indicating that HK2 expression was increased by ~100-fold in tumor cells relative to normal cells." (PMID 27588472, 2016). "Furthermore, multiple drugs have been developed which inhibit HK2 function and have been shown to be effective at decreasing tumor growth in preclinical testing." (PMID 27765905, 2016). "Data from patient tissues has suggested that the relative expression of KLK2 is increased in malignant tissue compared to benign and healthy prostatic tissue, and the intensity of hK2 immunostainings in, e.g., lymph node metastasis correlates better with PCa tumor grade than that of PSA." (PMID 26983637, 2016). "Hexokinase 2 (HK2) is also a key metabolic regulator implied in many tumor types." (PMID 27242914, 2016). "Additionally, it was also shown that decreasing expression of HK2 using shRNA both in vitro and in vivo slows the growth and metastatic potential of this tumor." (PMID 27765905, 2016). "The TN clusters (TN and TN+Her2) include proliferative proteins (MCM3 and 5), translation related proteins (RCL1, MRPS27, EIF2S2 and EEF1G) and metabolic enzymes (glutaminase and hexokinase 2), which reflect the higher dependence on glutamine and glucose of TN versus the other tumours." (PMID 26725330, 2016). "Our results confirm that HK1 and HK2 are involved in tumor growth maintenance." (PMID 28105937, 2016). "HK-2 is a hexokinase that is over-expressed in many tumours." (PMID 26616394, 2015). "In contrast, expression of GLUT 2, 3, 4, and HK2 was not correlated with tumor risk grade at both the mRNA and protein level." (PMID 26509967, 2015). "Although the underlying physiology remains unknown, this could be due to a decrease in an active uptake and/or the blocking of a pool of free hK2 in tumour tissue." (PMID 26116115, 2014). "Studies of tumors arising from targeted deletion of HK2 could lead to additional insights into metabolic reprogramming in tumorigenesis and the role of the tumor microenvironment." (PMID 23342984, 2013). "While not all hepatomas demonstrate hyperglycolysis, tumor glycolytic activity in HCC has been correlated with HK2 expression in tumors and the risk of cancer recurrence." (PMID 23071593, 2012). "It is thought that HK2 increases glycolysis in tumor cells and may therefore be an attractive therapeutic target." (PMID 22567347, 2011). "The expression of hexokinase 2 was consistent between the tumor perimeter and tumor core for both groups of tumors; with low and localized levels in the tumor sections developed from normoxic cells and highly profuse expression in the tumor sections developed from hypoxic cells." (PMID 21320311, 2011). "Further, the degree of expression of HK-2 could reflect the degree of neoplasm tissue transformation malignant." (PMID 20846459, 2010). "Therefore, future studies may investigate the role of HK2 in modulating mitochondrial function in T cells and its implications for anti-tumor immunity." (PMID 40181966, 2025). "However, CD8+ T cells, which are more reliant on glycolytic metabolism to fuel their cytotoxic activity, may depend more critically on HK2 in the tumor microenvironment." (PMID 40181966, 2025). "Notably HK2 inhibition also synergized with metformin or sorafenib to inhibit tumor growth." (PMID 40332478, 2025). "For example, HK2-mediated glycolysis contributes to the production of metabolic intermediates required for biosynthesis and energy generation in tumor cells, while simultaneously impairing immune cell function by depleting glucose availability in the tumor microenvironment." (PMID 40181966, 2025).
tumor (continued). "Furthermore, by enhancing glycolysis, HK2 exerts its influence on various metabolic pathways in tumor cells, such as pentose phosphate metabolism, glutamine metabolism, serine metabolism, and glycine metabolism, thereby playing a role in the occurrence and development of cancer." (PMID 39991762, 2025). "Therefore, the investigation of HK2 and its regulation of the tumor immune microenvironment may remain unclarified." (PMID 38581001, 2024). "Therefore, mechanistically, our research elucidated the effect of ARHGAP10 as a tumor suppressor that might inhibit the glycolysis metabolism of OC by inhibiting the PI3K/AKT/HK2 pathway." (PMID 38230565, 2024). "However, it is still unknown what instigates aberrant pericyte glycolysis in tumors and whether genetic ablation of HK2 in pericytes can impact tumor vasculature." (PMID 38798921, 2024). "To overcome these problems, we have used a cell-penetrating peptide called HK2pep that displaces HK2 from MAMs without targeting its catalytic activity, with the aim of eliciting tumor cell apoptosis while avoiding off-target effects caused by metabolic disruptions." (PMID 38995012, 2024). "Also, CAFs-derived WNT5A elevated HK2 expression and promoted GC tumor growth in vivo." (PMID 39054546, 2024). "However, HK2 activation in most tumour cells promotes metabolism and aerobic glycolysis." (PMID 39661501, 2024). "Moreover, the protein expression of HK2 in tumor tissues was elevated after MC-LR exposure." (PMID 39273011, 2024). "The main therapeutic approaches targeting HK2 include reducing its catalytic activity by inhibiting its expression, directly inhibiting its enzymatic activity to block glucose phosphorylation, and disrupting its interaction with mitochondria to cut off an important energy pathway for tumor cells." (PMID 39877360, 2024). "Interestingly, HK2 has proven to be critical for pericyte contractility during tumor angiogenesis." (PMID 38798921, 2024). "Similarly, it waspreviously reported that hexokinase 2 (HK2), a key glycolytic enzyme upregulated invarious cancer cells and required for oncogenictransformation and tumor development (Patraet al., 2013), undergoes degradation through CMA." (PMID 38829285, 2024). "Additionally, hypoxia-inducible transcription factor 1α (HIF-1α) could bind with the promoter of HK2 and promote its transcription to increase glycolytic flux for promoting tumor survival and growth." (PMID 37854321, 2023). "Thus, circACAP2 promotes tumor formation through the miR-143-3p/HK2 signal cascade." (PMID 37091173, 2023). "However, treatment with IR showed that HK2 overexpression could effectively enhance radio-resistance, whereas knockdown of HK2 elevated radio-sensitivity and inhibited tumor growth." (PMID 37524692, 2023). "However, it is unclear whether miRNAs regulate both tumor proliferation and metastasis through suppression of HK2-mediated aerobic glycolysis." (PMID 37019900, 2023). "Thus, circACAP2 promotes tumor formation by the miR-143-3p/HK2 signal cascade." (PMID 37091173, 2023). "In addition, HK2 can inhibit apoptosis and regulate autophagy in tumor cells." (PMID 37834257, 2023). "Importantly, in vivo tumor propagation was substantially blocked after HK2 knockdown, whereas it was strongly accelerated after HK2 overexpression." (PMID 35603967, 2022). "Targeting tumor HK2 expression might be a potential strategy for enhancing anti-tumor immunity." (PMID 36320008, 2022). "To confirm our hypothesis, through qRT–PCR assays we found that the expression of miR-143-3p significantly increased upon the low expression of CASC7, and correspondingly, the expression of HK2 significantly decreased upon the high expression of miR-143-3p in tumour cells." (PMID 35474307, 2022).